CYP11B2 (cytochrome P450 family 11 subfamily B member 2)
Description:
A cytochrome P450 monooxygenase that catalyzes the biosynthesis of aldosterone, the main mineralocorticoid in the human body responsible for salt and water homeostasis, thus involved in blood pressure regulation, arterial hypertension, and the development of heart failure. Catalyzes three sequential oxidative reactions of 11-deoxycorticosterone (21-hydroxyprogesterone), namely 11-beta hydroxylation, followed by two successive oxidations at C18 yielding 18-hydroxy and then 18-oxo intermediates (that would not leave the enzyme active site during the consecutive hydroxylation reactions), ending with the formation of aldosterone. Can also produce 18-hydroxycortisol and 18-oxocortisol, derived from successive oxidations of cortisol at C18, normally found at very low levels, but significantly increased in primary aldosteronism, the most common form of secondary hypertension. Mechanistically, uses molecular oxygen inserting one oxygen atom into a substrate and reducing the second into a water molecule. Two electrons are provided by NADPH via a two-protein mitochondrial transfer system comprising flavoprotein FDXR (adrenodoxin/ferredoxin reductase) and nonheme iron-sulfur protein FDX1 or FDX2 (adrenodoxin/ferredoxin). Besides its role in the biosynthesis of mineralocorticoids and glucocorticoids, it can also participate in the androgen metabolic pathway, converting testosterone (17beta-hydroxy-4-androsten-3-one) to 11beta,17beta-dihydroxyandrost-4-ene-3-one. Can also use progesterone as substrate.
Synonyms: ALDOS; CYP11BL; CPN2; P-450C18; P450aldo; CYP11B; CYPXIB2; P450C18
Tractability: Small molecule: an approved drug acts on it; a structure with a bound ligand is known; a high-quality ligand is known; it belongs to a druggable protein family. Antibody: UniProt places it where antibodies can reach, with medium confidence. PROTAC: a small molecule that binds it is known.
Target class: Enzyme; Cytochrome P450 family 11; Cytochrome P450 family 11B; Cytochrome P450 11B2; Cytochrome P450
Chemical probes: MSD-CYP11B2 (high quality), PD080765, PD083644
Gene: Protein-coding gene on chromosome 8 (142,910,559 to 142,917,850, reverse strand). Ensembl gene ENSG00000179142.
Subcellular location: Mitochondrion inner membrane
Subcellular location (Human Protein Atlas): Mitochondria
Pathways (Reactome):
Metabolism: Endogenous sterols; Glucocorticoid biosynthesis; Mineralocorticoid biosynthesis
Disease: Defective CYP11B2 causes CMO-1 deficiency
Gene Ontology:
Molecular function: heme binding; steroid 11-beta-monooxygenase activity; corticosterone 18-monooxygenase activity; steroid hydroxylase activity; iron ion binding; monooxygenase activity; oxidoreductase activity, acting on paired donors, with incorporation or reduction of molecular oxygen
Biological process: aldosterone biosynthetic process; C21-steroid hormone biosynthetic process; cellular response to hormone stimulus; cellular response to potassium ion; cortisol biosynthetic process; potassium ion homeostasis; regulation of blood volume by renal aldosterone; sodium ion homeostasis; cellular response to peptide hormone stimulus; cholesterol metabolic process; cortisol metabolic process; glucocorticoid biosynthetic process; mineralocorticoid biosynthetic process; renal water homeostasis; sterol metabolic process
Cellular component: mitochondrion; mitochondrial inner membrane
Genetic constraint (gnomAD): Loss-of-function variants: 38 observed, 49.44 expected, observed/expected ratio (o/e) 0.77, 90% interval 0.59 to 1.01. The upper end of that interval is the gene's LOEUF score, 1.01, which puts it in group 4 of 6, group 1 being the genes least tolerant of losing a copy. Missense variants: 669 observed, 669.75 expected, observed/expected ratio (o/e) 1, 90% interval 0.94 to 1.07. Synonymous variants: 290 observed, 277.03 expected, observed/expected ratio (o/e) 1.05, 90% interval 0.95 to 1.15.
Gene-disease validity (ClinGen):
ClinGen rates the evidence that CYP11B2 causes each of these diseases.
familial hyperreninemic hypoaldosteronism type 2 (autosomal recessive): Definitive.
Homologues: Orthologues: macaque CYP11B2 (95% identical), macaque CYP11B1 (93% identical). Paralogues in human: CYP11B1 (93% identical), CYP11A1 (38% identical).
Diseases named in the same sentence as CYP11B2 in open-access papers:
CYP11B2 is named in the same sentence as 97 diseases in open-access papers, as found by Europe PMC text mining. Sharing a sentence is not in itself a finding about the gene and the disease. The quoted sentences say what the papers report.
Hypertension (95 papers, 2009 to 2026). The presence of chronic increased pressure in the systemic arterial system. "Lastly, the CYP11B2 (cytochrome P450 family 11 subfamily B member 2) gene is part of the renin–angiotensin–aldosterone system, and its variants are associated with hypertension and CKD." (PMID 40149623, 2025). "One study revealed that the interaction between alcohol consumption and the CYP11B2 risk genotype is associated with a threefold increase in the risk of hypertension." (PMID 41152890, 2025). "A study involving 1575 Chinese individuals identified a significant interaction between alcohol consumption and hypertension risk linked to a polymorphism (−344TC) in the cytochrome P450 family 11 subfamily B member 2 (CYP11B2) gene." (PMID 38786976, 2024). "A study on people with hypertension found that the aldosterone-secreting CYP11B2-344T > C polymorphism was also associated with the development of AF." (PMID 37340493, 2023). "The ovaries play a role in the synthesis of estrogen and other hormones, and differences in the expression of ovarian steroidogenesis genes, such as CYP17A1 and CYP11B2, have been linked to a higher risk of hypertension." (PMID 37571339, 2023). "The present study investigates the relationship between CYP11B2 gene polymorphism and hypertension in Pakistan’s Pashtun population." (PMID 37372364, 2023). "Y.R. Kim and colleagues investigated the relationship between variants -344C/T of CYP11B2 gene and hypertension in Korean patients." (PMID 37372364, 2023). "Niu et.al, in a study of Japanese populations, found strong positive associations between CYP11B2 gene polymorphism and the development of hypertension." (PMID 37372364, 2023). "Studies have shown that the ACE I/D polymorphism, the ACE2 G8790A polymorphism, and the CYP11B2-344T/C polymorphism are related to the occurrence of hypertension." (PMID 35130889, 2022). "Among them, three DEGs (Cyp11b2, Ptgds, and Slc6a3) were found to be associated with both behavior and hypertension." (PMID 36140769, 2022). "Previous studies on the relationship between ACE I/D, ACE2 G8790A and CYP11B2-344T/C gene polymorphisms and essential hypertension (EH) were inconsistent." (PMID 35130889, 2022). "For example, variants of the CYP11B2 locus have been frequently validated to be associated with hypertension in multiple populations." (PMID 34593835, 2021). "Related studies have shown that there is a significant association between the CYP11B2 (-344C/T) polymorphism and the -344T allele and essential hypertension." (PMID 33761712, 2021). "Compared with CYP11B2 rs1912 CC genotype, the OR of hypertension risk was 2.82 (95% CI: 1,57–5.06) for TT genotype." (PMID 31484569, 2019). "ACE rs4425, ACE rs4337, ART rs129876 and CYP11B2 rs1912 polymorphism were associated with an increased risk of hypertension in mutant homozygous genotype." (PMID 31484569, 2019). "In this study, other variants that were reported in association with hypertension in the same population included CYP11B2, which encodes for aldosterone synthase." (PMID 30832344, 2019). "We used a candidate association approach to report an association between the AG genotype of CYP11B2 rs542092383 with an increased risk of hypertension in the Han population of northern China." (PMID 28953657, 2017). "Polymorphisms of the aldosterone synthase gene (CYP11B2) have been reported to be associated with essential hypertension (EH)." (PMID 28953657, 2017). "CYP11B2 plays a significant role in the biosynthesis of aldosterone which can cause a series of diseases, including hypertension." (PMID 27781210, 2016). "Previous studies demonstrated that the polymorphic variation of CYP11B2, the gene encoding aldosterone synthase, was associated with increased aldosterone metabolite excretion and hypertension." (PMID 28078278, 2016).
Hypertension (continued). "According to the chi-square test P values (P<0.05) and odds ratios, rs3789678 and rs2493132 within AGT, rs4305 within ACE, rs275645 within AGTR1, rs3802230 and rs10086846 within CYP11B2 were shown to associate with hypertension." (PMID 24015270, 2013). "According to Chi-square test and logistic regression analysis, rs3789678 within AGT, rs4305 within ACE, rs275645 within AGTR1, rs3802230 within CYP11B2 were shown to associate with hypertension." (PMID 24015270, 2013). "Of 41 SNPs genotyped, rs3789678 and rs2493132 within AGT, rs4305 within ACE, rs275645 within AGTR1, rs3802230 and rs10086846 within CYP11B2 were shown to associate with hypertension." (PMID 24015270, 2013). "We refer to recent reviews on the genetics of the renin–angiotensin–aldosterone system, G-proteins, adducin, and oxidative stress in hypertension, but will discuss the association of the aldosterone synthase gene (CYP11B2) with hypertension as an exemplar." (PMID 20035862, 2010). "The haplotypes in CYP11B2 is strongly associated with hypertension or plasma aldosterone concentrations." (PMID 19243623, 2009). "There is a correlation between CYP11B2 polymorphism and a higher risk of hypertension." (PMID 38786976, 2024). "Polymorphic variation in CYP11B2 is linked to an increased chance of hypertension." (PMID 37372364, 2023). "Polymorphisms in the CYP11B2 gene are linked to an increased risk of hypertension." (PMID 37372364, 2023). "According to studies, people who have CYP11B2 gene variants may be at a higher risk of developing hypertension." (PMID 37571339, 2023). "In addition to the CYP11B1/CYP11B2 chimeric gene, there are some SNPs at the CYP11B1 and CYP11B2 loci that are also associated with hypertension." (PMID 35012455, 2022). "Also, we identified 18 loci with suggestive association, 14 of which were previously reported to be associated with hypertension or blood pressure (e.g. the CYP11B2 or CACNA1D locus)." (PMID 34593835, 2021). "In addition, our study revealed that some variants at the CYP11B2 locus, which were reported to be associated with both hypertension and blood pressure, showed a suggestive association with resistant hypertension in this GWAS." (PMID 34593835, 2021). "The SNP −344C/T (rs179998) in the CYP11B2 gene encoding aldosterone synthase, which catalyzes the final step of aldosterone production in juxtaglomerular cells, was shown to modulate aldosterone level, hypertension susceptibility, and blood pressure responses to ARB." (PMID 32630286, 2020). "This study provides evidence that age, BMI, diabetes, preference for fried or barbecued foods and polymorphism in the ACE, ATR, and CYP11B2 genes of the RAAS system were associated with elevated risk of hypertension among Hui Hajj pilgrims in Gansu Province, China." (PMID 31484569, 2019). "However, a recent meta-analysis was not able to show the association of the SNPs of ACE, AGT, and CYP11B2 genes and hypertension." (PMID 31511791, 2019). "The T-G-T haplotype of CYP11B2 was also associated with hypertension susceptibility." (PMID 28953657, 2017). "Aldosterone synthase (CYP11B2) is closely linked to essential hypertension (EH)." (PMID 28078278, 2016). "From a cohort of more than 1500 unrelated subjects referred for evaluation of genetic forms of hypertension, we identified 40 subjects diagnosed with hypertension and PA by age 10 years in whom disease-causing mutations in CYP11B2, KCNJ5, and CACNA1D were excluded." (PMID 25907736, 2015). "Mutations in CYP11B2 can lead to important changes to arterial pressure and could be responsible for hypertension." (PMID 19243623, 2009). "This identifies CYP11B2 as a locus harbouring at least one common polymorphism of functional effect that could influence blood pressure and predispose carriers of the “derepressed” C allele to hypertension." (PMID 28272372, 2017).
Hypertension (continued). "This Review summarizes the pathophysiology of aldosterone in hypertension, the molecular pharmacology of CYP11B2 inhibition, the discovery and development of Baxdrostat, and its clinical evaluation." (PMID 41988370, 2026). "Osilodrostat, a dual CYP11B1 and CYP11B2 inhibitor, has shown efficacy in patients with Cushing’s syndrome, particularly those with coexisting hypertension and metabolic disturbances." (PMID 41154669, 2025). "The elevated expression and dysregulated distribution of CYP11B2 lead to renin-independent hyperaldosteronism, resulting in the spontaneous hypertension in MU." (PMID 39946402, 2025). "As per the fitted model, the CYP11B2 r1799998 CT and rs1799998 TT genotype and ACE rs4646994 ID genotype resulted in a decreased risk of developing hypertension, with odds ratios of 0.2017, 0.0538, and 0.4329, respectively." (PMID 38541065, 2024). "In conclusion, exploring CYP11B2 inhibitors presents a promising avenue for managing PA and hypertension." (PMID 39170743, 2024). "Baxdrostat is one of the selective CYP11B2 inhibitors that had completed a phase 2 clinical trial for treatment of patients with treatment-resistant hypertension." (PMID 39170743, 2024). "Five variants (CYP11B2 rs179998, AGT rs5051 and rs699, AGTR1 rs5186, and ACE rs4646994) were significantly associated with essential hypertension in the cohort under study." (PMID 38541065, 2024). "Several genes, including CYP17A1, CYP11B2, HSD11B1, CYP11B1, and NR3C2, which are implicated in the control of hypertension, regulate the synthesis of steroid hormones, such as glucocorticoids, mineralocorticoids, androgens, and estrogens." (PMID 37571339, 2023). "On the other hand, the AGTR1 and CYP11B2 genes are linked to the ACE inhibitor pathway and are used to treat cardiovascular disorders such as hypertension." (PMID 35629146, 2022). "The analysis revealed three genes (Cyp11b2, Ptgds, and Slc6a3) related to both hypertension and the behavior/neurological phenotype." (PMID 36140769, 2022). "Glucocorticoid-remediable aldosteronism (GRA) is a form of heritable hypertension caused by a chimeric fusion resulting from unequal crossing over between 11β‐hydroxylase (CYP11B1) and aldosterone synthase (CYP11B2), which are two genes with similar sequences." (PMID 35012455, 2022). "CYP11B2 is one of the most important genes that regulate hypertension manifestation due to its role as a key enzyme in aldosterone biosynthesis and aldosterone synthase." (PMID 35629146, 2022). "Age, gender, BMI, family history of hypertension, adjusted CYP11B2 and CYP11B1 H-scores differed significantly between complete clinical success and incomplete clinical success groups." (PMID 34631800, 2021). "SNPs in several other genes have also been shown to be associated with hypertension such as A1161 polymorphism in angiotensin II type I receptor gene (AGTR1) and CYP11B2 gene polymorphism." (PMID 31906879, 2020). "Aldosterone synthase, which is needed to synthesize aldosterone, has a genetic polymorphism, CYP11B2 rs1799998, that is associated with hypertension." (PMID 31511791, 2019). "This study aimed to investigate the association between 4 polymorphisms in RAAS genes (i.e., rs1799752 (ACE), rs699 (AGT), rs5186 (AGTR1), and rs1799998 (CYP11B2)) and hypertension in a Thai population." (PMID 31511791, 2019). "Similar results were also observed for ATR and CYP11B2 genotypes: compared with ATR rs129876 GG genotype, the OR of hypertension risk was 4.10 (95% CI: 2.30–7.32) for AA genotype." (PMID 31484569, 2019). "Using 4,150 Thais recorded in the Electricity Generating Authority of Thailand (EGAT) study, we examined the association of rs1799752, rs699, rs5186, and rs1799998 located in or near ACE, AGT, AGTR1, and CYP11B2 genes in hypertension." (PMID 31511791, 2019). "By contrast, for low-renin hypertension, a two-locus model that includes the GRK4 A142V variant and cytochrome P450 11B2 (CYP11B2) C-344 T was 77.8% predictive." (PMID 30621627, 2019).